HGF (hepatocyte growth factor)
Diseases named in the same sentence as HGF in open-access papers (continued):
Sharing a sentence is not in itself a finding about the gene and the disease.
hepatocellular carcinoma (continued). "Hepatocellular carcinoma cell line H22 can express hepatocyte growth factor (HGF), which is a potent stimulator of DNA synthesis in a variety of epithelial cells, including hepatocytes, and has been implicated in liver regeneration." (PMID 26508976, 2015). "The key signal transduction pathways that have been implicated in the pathogenesis of hepatocellular carcinoma are the EGFR, Ras/Raf/Mek/Erk, phosphoinositide 3-kinase/Akt, mTOR, HGF/c-Met, Wnt, and Hedgehog signaling cascades." (PMID 25895026, 2015). "Raf1 phosphorylation on serine 259 by Akt has also been shown in the HGF stimulated human hepatoma cell line Hep3B." (PMID 25905717, 2015). "Hepatocellular carcinoma (HCC) patients with active hepatocyte growth factor (HGF)/c-Met signaling have a significantly worse prognosis." (PMID 25886575, 2015). "Other treatments that stimulate ERK phosphorylation in hepatoma cells that had been previously shown to upregulate LDL uptake include HGF, FGF21, hGH, PMA and AICAR." (PMID 25811180, 2015). "c-Met, the receptor for Hepatocyte Growth Factor (HGF), overexpressed and deregulated in Hepatocellular Carcinoma (HCC)." (PMID 25148256, 2014). "C-Met, also known as the hepatocyte growth factor (HGF) receptor, has been implicated in the development of hepatocellular carcinoma." (PMID 23418453, 2013). "It was also reported that HGF upregulation promoted carcinogenesis and epithelial-mesenchymal transition in hepatocellular carcinoma via Akt and COX-2 pathways." (PMID 23622143, 2013). "In the hepatoma cells, HGF promoted gene expression by increasing HIF activity, and in the HGF-induced survival in carcinoma cells, involved HIF-1α activation." (PMID 23209838, 2012). "In patient 1, serum AFP, which is known to increase not only during development of hepatocellular carcinoma but also liver regeneration, modestly increased during the rh-HGF dosing period, followed by a gradual decrease during the observation period." (PMID 21548996, 2011). "Clinical observations suggest that hepatocyte growth factor HGF (known as scatter factor, SF) and its receptor, the c-Met tyrosine kinase, can promote metastasis of hepatoma cells while stimulating tumor invasiveness." (PMID 18946424, 2008). "For example, ALDH1A1 (stress response) and MAPK3 (cell proliferation) are targets of the HGF/MET signaling pathway which has been associated with tumor metastasis and poor prognosis in human hepatocellular carcinomas." (PMID 17900369, 2007). "The HGF/c-MET signaling pathway plays a crucial role in cell proliferation, migration, invasion, and survival, with its dysregulation implicated in various cancers, including hepatocellular carcinoma (HCC)." (PMID 40867270, 2025). "Additionally, C1GALT1 has been shown to modify O‐glycosylation of receptor tyrosine kinases, such as MET with the enhancement of HGF‐induced activation in hepatocellular carcinoma." (PMID 39844613, 2025). "In hepatocellular carcinoma, silibinin has been found to effectively abate hepatocarcinogenesis and hepatocellular carcinoma growth by regulating various signaling pathways including HGF/c-Met, Wnt/β-catenin and PI3K/Akt/mTOR." (PMID 37456742, 2023). "Consequently, it inhibits HGF-induced hepatocellular carcinoma cell migration, motility, spheroid formation, and liver tumor growth in vivo." (PMID 36551220, 2022). "Here, we hypothesized that the HGF/Met signaling pathway promotes stemness properties in CD44v6+ hepatocellular carcinoma (HCC) cells via overexpression of the transcription factor, cJun, thus representing a valuable target for HCC therapy." (PMID 36387747, 2022). "Clinical trials of some HGF/c-Met signaling inhibitors in hepatocellular carcinoma patients." (PMID 36505831, 2022).
hepatocellular carcinoma (continued). "Hepatocellular carcinoma (HCC)-specific computational model of HGF/c-Met axis supports the findings of experimental studies reporting enhanced inhibition of phosphorylated AKT and ERK1/2 upon c-Met-α5β1 dissociation and highlights the importance of previously identified c-Met-β1 co-trafficking." (PMID 36330337, 2022). "In addition, the activation of the HGF/c−MET axis promotes lenvatinib resistance in hepatocellular carcinoma cells." (PMID 36505831, 2022). "The HGF-mediated c-Met/FRA1/HEY1 cascade may be the key to inducing the transition from cirrhosis to hepatocellular carcinoma." (PMID 33718161, 2021). "We herein summarize and discuss studies focused on partial hepatectomy and liver carcinogenesis, referring to hepatocyte growth factor, insulin-like growth factor, and epidermal growth factor, as well as their suitability as targets in the treatment of hepatocellular carcinoma." (PMID 34572344, 2021). "miRNAs that target HGF/c-Met signaling in hepatocellular carcinoma." (PMID 32117981, 2020). "Drugs targeting HGF/c-Met in hepatocellular carcinoma patients." (PMID 32117981, 2020). "TAMs in hepatocellular carcinoma contribute to chemoresistance by inducing HGF." (PMID 31629410, 2019). "GM-CSF derived from hepatoma cells could induce neutrophils to secrete HGF, which in turn leads to the migration and invasion of hepatoma cells." (PMID 29556041, 2018). "In hepatocellular carcinoma, miR-198-5p has been shown to target the HGF/c-MET pathway." (PMID 29394946, 2018). "In addition, ROS-induced invasive activity of hepatoma cells has been demonstrated to be mediated through an autocrine/paracrine loop of HGF, where ROS directly augment mRNA expression of HGF." (PMID 29296173, 2017). "In addition, it is of interest to investigate the involvement of c-Met-Arf6-PIP5K1A signaling in hepatocellular carcinoma, since dysregulation of HGF/c-Met is highly related to this disease." (PMID 28842595, 2017). "In addition, patients with hepatocellular carcinoma also showed decreased HGF concentrations after sorafenib treatment." (PMID 27203677, 2016). "Moreover, sorafenib attenuated HGF secretion in polarized macrophages, and decreased plasma HGF in patients with hepatocellular carcinoma." (PMID 27203677, 2016). "Previous study has reported that HGF induces EMT in hepatocellular carcinoma." (PMID 26919096, 2016). "Similarly, hepatocellular carcinoma cells stimulated neutrophils to release hepatocyte growth factor (HGF)." (PMID 26819959, 2015). "p21 was up-regulated by HGF addition, and mediated growth inhibition in a hepatoma cell-line." (PMID 24223793, 2013). "In hepatocellular carcinoma (HCC), sorafenib resistance is induced by the delivery of hepatocyte growth factor (HGF) through EVs, which activates the HGF/c-MET/PI3K/AKT signaling pathway." (PMID 40475777, 2025). "For instance, in hepatocellular carcinoma (HCC) cell lines, EVs carrying hepatocyte growth factor (HGF) have been shown to induce resistance to Sorafenib both in vitro and in vivo." (PMID 39403600, 2024). "FIS1 Y38 phosphorylation by Met tyrosine kinase, a receptor for hepatocyte growth factor (HGF), promotes mitochondrial fission and facilitates hepatocellular carcinoma (HCC) tumor growth." (PMID 37627290, 2023). "Hepatocellular carcinoma (HCC)‐derived GM‐CSF accelerates tumor progression through stimulating TANs to produce hepatocyte growth factor and activate hepatocyte growth factor/Met axis." (PMID 35612789, 2022). "Additionally, in vivo and in vitro resistance to sorafenib in hepatocellular carcinoma cell lines was induced by the EV-mediated delivery of HGF and subsequent HGF/c-MET/PI3K/AKT signaling pathway activation, a major oncogenic signaling axis involved in cancer cell proliferation and survival." (PMID 32150875, 2020).
hepatocellular carcinoma (continued). "In hepatocellular carcinoma (HCC) invasive cell lines, in vitro and in vivo resistance to Sorafenib is caused by the distribution of hepatocyte growth factor (HGF), with the assistance of T-EVs and the subsequent activation of the HGF/c-MET/PI3K/AKT signalling pathway." (PMID 33081785, 2020). "We demonstrated M2, but not M1, macrophages not only promote proliferation, colony formation and migration of hepatoma cells but also significantly confer tumour resistance to sorafenib via sustaining tumour growth and metastasis by secreting hepatocyte growth factor (HGF)." (PMID 31130723, 2019). "Hepatocellular carcinoma (HCC) patients with activated HGF/c-Met signaling have a significantly worse prognosis." (PMID 26000702, 2015). "In the present study, we used HGF induced EMT metastasis model in Huh7 hepatocellular carcinoma cells for exploring the mechanism of HCC metastasis." (PMID 23977005, 2013). "Activation of HGF/c-Met signaling has been correlated with aggressive phenotype and poor prognosis in hepatocellular carcinoma (HCC)." (PMID 22962849, 2012). "Hepatocyte growth factor (HGF) and its receptor c‐Met inhibitors increase antitumor immunity by reversing EMT in various malignancies, notably hepatocellular carcinomas." (PMID 40895189, 2025). "For example, miR-26a-5p is reduced in hepatocellular carcinoma (HCC) and can inhibit tumor angiogenesis through HGF-cMet signaling." (PMID 38446584, 2024). "Gab1 knockdown in mouse hepatoma cells treated with CCL4 alone, or CCL4 plus HGF, showed a significant increase in cleaved caspase-3, along with decreased pERK1/2 and pSTAT3, as compared to control cells." (PMID 38935609, 2024). "Suppressing the downstream pathway of the HGF/MET axis, including phosphoinositide 3-kinase (PI3K)/AKT, RAS-RAF-MEK-ERK, and JAK/STAT, hinders the invasion and metastasis of hepatoma cells." (PMID 38881894, 2024). "Hepatoma cells showed elevation of p-Gab1, along with an increase in STAT3 and ERK activation, upon treatment with HGF (ligand of HGF receptor/c-Met) and CCL4." (PMID 38935609, 2024). "In vitro, HGF and IGF secreted by CD163+ macrophages were sufficient to induce hepatoma cell proliferation." (PMID 36845555, 2023). "Studies have revealed that EZH2 elevates hepatocyte growth factor (HGF) and macrophage migration inhibitory factor (MIF) in hepatocellular carcinoma, which contribute to M2 repolarization and poor prognosis." (PMID 36038549, 2022). "In hepatocellular carcinoma, CYP1A2 inhibits cancer progression through antagonizing HGF/MET signaling." (PMID 36110953, 2022). "This is evident with the demonstration that growth factors such as CCL2 and hepatocyte growth factor (HGF) induced CSC renewal and stemness of cancer cells in both breast and hepatocellular carcinoma." (PMID 34122412, 2021). "In hepatocellular carcinoma cells, EGR1 induced by hepatocyte growth factor (HGF) can directly bind to the promoter region of SNAIL, increase its expression, and lead to tumor cell metastasis." (PMID 33842351, 2021). "Alterations in HGF and MET expression are commonly reported in different types of cancers such as non-small cell lung cancer (NSCLC), GI tumors, and hepatocellular cancer (HCC)." (PMID 34037097, 2021). "We have also shown that targeting the c-Met/FRA1/HEY1 cascade mediated by HGF could be a promising treatment strategy for hepatocellular carcinoma (HCC) since the tumor-initiating cells of the liver are regulated by CAFs together with HGF secretions." (PMID 34202411, 2021). "In hepatocellular carcinoma cells, EMT induced by HGF reduced the expression of MGAT3 but increased that of MGAT5, FUT8 and B3GALT5." (PMID 34356834, 2021). "Hepatocyte growth factor (HGF)/c-mesenchymal–epithelial transition receptor (c-Met) pathway can regulate tumor growth and metastasis in hepatocellular carcinoma (HCC) cells." (PMID 33167504, 2020).
hepatocellular carcinoma (continued). "Hepatocyte growth factor (HGF) and MET signaling supports cellular proliferation, promotes epithelial-mesenchymal transition (EMT) and causes invasion and metastasis during malignant transformation in hepatocellular carcinoma (HCC)." (PMID 32878084, 2020). "Sorafenib resistance is one of the major obstacles towards achieving a better outcome in patients with advanced hepatocellular carcinoma (HCC), in which aberrant activation of the hepatocyte growth factor (HGF)/mesenchymal‐epithelial transition pathway is frequently observed." (PMID 30761258, 2019). "To further explore underlying mechanisms, we assessed the expression and phosphorylation of key proteins in HGF/c-Met, ERK/MAPK and PI3K/AKT pathways in hepatoma cells." (PMID 31130723, 2019). "In hepatocellular carcinoma (HCC) invasive cells lines, resistance to Sorafenib in vitro as well as in vivo was induced by delivery of hepatocyte growth factor (HGF) through EVs and subsequent activation of the HGF/c-MET/PI3K/AKT signaling pathway." (PMID 30925923, 2019). "HGF activates HGF/c-Met, MAPK/ERK1/2, and PI3K/AKT pathways in tumour cells, further recruits M2 TAMs, and thus sustains hepatoma growth and metastasis in a feed-forward manner." (PMID 31130723, 2019). "It was shown that HGF, together with its ligand MET (HGF/MET), promotes cell proliferation, survival, migration, and angiogenesis in hepatocellular carcinoma." (PMID 26859576, 2016). "Sorafenib also inhibited polarized macrophage-induced Met activation in hepatocellular carcinoma cells, suggesting that sorafenib inhibited macrophage-induced EMT and migration of hepatocellular carcinoma cells via the HGF-Met signaling pathway." (PMID 27203677, 2016). "Accordingly, reciprocal signaling between hepatic stellate cells and precancerous hepatoma cells induced an EMT and CSC-like properties in HCC mediated by hepatocyte growth factor (HGF)/Met signaling." (PMID 27578206, 2016). "HGF-mediated responses of PI3K signaling were monitored both at the single cell and cell population level in primary mouse hepatocytes and in the hepatoma cell line Hepa1_6." (PMID 23226133, 2012). "HSulf1 expression is decreased in 82% of hepatocellular carcinoma (HCC) cell lines, leading to increased HSPG sulfation, enhanced FGF-mediated and hepatocyte growth factor (HGF)-mediated signaling, and increased cell growth." (PMID 20707913, 2010). "In hepatocellular carcinoma (HCC) and gastric cancer, miR-26a-5p expression has been reported to inhibit proliferation, migration, and invasion by downregulating oncogenic signaling pathways (e.g., the HGF-Met and COL10A1 pathways)." (PMID 39288140, 2024). "Consequently, they suggest that targeting the c-Met/FRA1/Hey1 cascade mediated by CAF-derived HGF could serve as a potential therapeutic approach for hepatocellular carcinoma (HCC)." (PMID 38791916, 2024). "Moreover, studies have shown that HGF/c-Met can regulate the YAP pathway thereby promoting proliferation and migration of tumor cells leading to stemness maintenance of CSLCs in hepatocellular carcinoma and prostate cancer." (PMID 38634107, 2024). "Besides, sustained activation of oncogene signaling such as RHO GTPase related signaling, HGF/c-MET signaling, PI3K/AKT signaling, NRAS/ERK signaling, is a key driver of hepatocellular carcinoma (HCC) progression." (PMID 38254216, 2024). "In addition, another study found that HGF activated C/EBPβ and cell replication via the PI3K signaling pathway in rat hepatocellular carcinoma cells." (PMID 36766839, 2023). "Moreover, LPAR6 promotes hepatocellular carcinoma proliferation via the NCOA3-LPAR6-HGF signaling cascade, and the tumor-suppressive effect by depletion of LPAR6 is similar to that of anti-HGF treatment." (PMID 34209775, 2021). "In addition, luteolin inhibited the migration and invasion of HGF‐induced HepG2 cells by suppressing the phosphorylation of c‐Met, ERK, and Akt in hepatoma (Lee, Wu, Chen, Wang, & Tseng, 2006)." (PMID 30653763, 2019).
hepatocellular carcinoma (continued). "In hepatocellular carcinoma (HCC), activated HSCs induce phenotypic changes in oncogenic hepatocytes, notably through the production of growth factors and cytokines such as HGF (hepatocyte growth factor) and IL6 in favor of tumor cell proliferation." (PMID 29855567, 2018). "After treatment with sorafenib, HGF secretion was decreased in macrophages, which reduced the polarized macrophage-conditioned medium-induced activation of HGF-Met signaling in hepatocellular carcinoma cells but not in normal liver cells." (PMID 27203677, 2016). "We also found that CAPS1 decreased the levels of SDF-1, HGF, and TGF-β in hepatoma cells." (PMID 27689999, 2016). "Moreover, quercetin also inhibited HGF-induced c-Met phosphorylation in human medulloblastoma cell line DAOY, and suppressed HGF-stimulated migration and invasion in DAOY cells and human hepatoma HepG2 cells." (PMID 25971889, 2015). "Nevertheless, in HepG2 hepatocellular carcinoma and Madin-Darby canine kidney (MDCK) cells, a direct KLF4-mediated downregulation of CDH1 was observed, downstream of hepatocyte growth factor (HGF, also known as scatter factor/SF)-induced cell scattering." (PMID 24429391, 2014). "Collectively, secreting HGF into tumor milieu, HSCs may decrease hepatoma cells sensitization to chemotherapeutic agents by promoting EMT and CSC-like features via HGF/Met signaling." (PMID 24023859, 2013). "The rat ascites hepatoma cell line, AH109A, expresses HGF and c-Met mRNAs." (PMID 19497102, 2009). "In addition, the HGF-antagonist NK4 inhibits c-met signalling and angiogenesis in vitro and reduces intratumoural microvessel density in a hepatocellular carcinoma xenograft model." (PMID 17244359, 2007). "Hepatocyte growth factor (HGF) and its receptor c-Met were frequently deregulated in hepatocellular carcinoma (HCC)." (PMID 26840563, 2016). "For example, aberrant NRF2 activation has been identified to accelerate the development of hepatocellular carcinoma (HCC) from pre-cancerous lesions and the HGF/c-Met axis is fundamentally involved in HCC pathogenesis via canonical and non-canonical pathways." (PMID 35087852, 2021). "Conclusion: miR-17-5p and miR-20a-5p could suppress postoperative metastasis of hepatocellular carcinoma via blocking HGF/ERBB3-NF-κB positive feedback loop and offer a new probable strategy for metastasis prevention after HCC resection." (PMID 32206115, 2020). "Similarly, HGF/c-Met inhibitors such as tivantinib failed to improve survival in advanced hepatocellular carcinoma (METIV-HCC, NCT01755767), raising caution for analogous strategies in CCA." (PMID 41445734, 2025).